CRP (C-reactive protein)
Diseases named in the same sentence as CRP in open-access papers (continued):
Sharing a sentence is not in itself a finding about the gene and the disease.
Sepsis (continued). "The ROC assessment of the diagnostic power of the biomarkers and CRP showed that APOA5, copeptin and CRP levels had excellent AUC values (0.965, 0.960, and 0.917, respectively) for sepsis diagnosis." (PMID 36755189, 2023). "This study aimed to investigate the relationship between the C-reactive protein (CRP) trajectories of patients with sepsis in the intensive care unit (ICU) and the in-hospital mortality rate." (PMID 37709919, 2023). "Five groups with different CRP and ferritin trajectories were identified in critically ill pediatric patients with sepsis, with the mortality rate showing among-group differences." (PMID 37709919, 2023). "IL-1Ra and IL-6 increased significantly 2 days before the diagnosis of sepsis, and both emerged superior at predicting sepsis when compared to clCAM-1 and CRP one or more days before clinical diagnosis." (PMID 36769133, 2023). "Compared to other biomarkers such as C-reactive protein, necrosis factor-alpha, and interleukins, procalcitonin has been shown to be more sensitive and specific in sepsis diagnosis." (PMID 37407641, 2023). "C-reactive protein is a highly sensitive marker for tissue injury and inflammation and is often used as a marker for sepsis, Crohn’s disease, and inflammatory bowel disease in humans and animals." (PMID 36670767, 2023). "The ROC analysis showed that the MHLA-DR expression rate was the biomarker with the highest specificity, and CRP was the one with the highest sensitivity to predict sepsis." (PMID 37509475, 2023). "In septic shock, changes in the values of creatinine, PCT and CRP concentrations followed a similar trend as observed in case of sepsis." (PMID 36767629, 2023). "PCT is one of the extensively investigated sepsis biomarkers also employed in pneumonia in a wide range of studies, together with CRP and a complete blood count." (PMID 37296721, 2023). "They found CRP/albumin to be statistically significant for exitus, infection, sepsis and liver failure." (PMID 38024343, 2023). "In the present study, we propose to investigate the role of HLA-DR expression on monocytes, the sepsis index (ratio between NCD64 and MHLA-DR), and CRP as predictive biomarkers of sepsis." (PMID 37509475, 2023). "In our study, PCT confirmed high specificity in recognition of patients with sepsis, showing a greater positive prognostic value as compared with CRP and NEUT-RI." (PMID 37238265, 2023). "As for the evaluation of CRP performance for the detection of sepsis, 87 values were analyzed, showing a significant difference between “non-septic” and “septic” group (3.3 [1.43; 11.2] mg/dL vs. 18.1 [8.3; 25.3] mg/dL, p < 0.001)." (PMID 37238265, 2023). "The results show that MIP is widely applicable in the determination of CRP—a biomarker of inflammation and sepsis." (PMID 37366985, 2023). "Our findings demonstrated that the in-hospital mortality rates in critically ill patients with sepsis differed according to the CRP trajectories, with a certain level of clinical significance." (PMID 37709919, 2023). "Serum suPAR is dramatically elevated during sepsis and represents a potential biomarker for predicting its severity better than many other biomarkers, such as CRP and PCT." (PMID 37569751, 2023). "Similar heterogeneity is seen across other sepsis biomarker studies, including CRP and procalcitonin." (PMID 38012554, 2023). "In our study, two non-colonized patients of the low VAP suspicion group with declining CRP levels developed sepsis, increasing CRP levels at least threefold between the two monitored timepoints." (PMID 37237823, 2023). "Regarding laboratory tests, several biomarkers such as TNFα, IL-1, IL-10, IL-6, serum procalcitonin (PCT), and C-reactive protein (CRP) are currently being used to detect sepsis." (PMID 37189528, 2023). "Only very few studies evaluated the predictability of salivary CRP for sepsis and have found it to have good predictability, with varying AUC values of 0.886 and 0.63, respectively." (PMID 36900011, 2023).
Sepsis (continued). "Based on our findings, the median serum PCT concentration was higher in the sepsis group and around 0 in the non-sepsis group, similar to serum CRP concentration." (PMID 36834338, 2023). "Initially, we conducted two-sample MR analyses to examine the effect of C-reactive protein levels on sepsis and its subgroups." (PMID 37662942, 2023). "In the ICU settings, a number of biomarkers have been well studied as diagnostic tools for early detection of sepsis such as PCT, CRP, and WBC." (PMID 37189528, 2023). "Recently, several serum (or plasma) biomarkers have been proposed for the timely diagnosis and prognostications of patients with sepsis, including C-reactive protein (CRP), procalcitonin (PCT), presepsin, and interleukin 6 (IL-6)." (PMID 37324133, 2023). "SIRS-specific biomarkers MPP3, PLA2G7, GPR124 and ARHGEF10L correlated positively with each other and negatively with the sepsis-specific biomarkers and CRP." (PMID 38332914, 2023). "Multivariate logistic regression analysis revealed that the PNI, NLR, international normalized ratio (INR), thrombin time (PT), and C-reactive protein (CRP) were independent prognostic factors for DFU-induced sepsis." (PMID 38026334, 2023). "Interleukin-1 (IL-1), IL-6, C-reactive protein and other inflammatory mediators stimulate TF expression on the surface of endothelial cells under inflammatory conditions such as sepsis and acute lung injury, leading to hypercoagulability." (PMID 37693903, 2023). "The aim was to evaluate the HLA-DR expression on the surface of monocytes (MHLA-DR ratio), the sepsis index (CD64 expression on neutrophils/MHLA-DR ratio), and C-reactive protein (CRP) with the development of sepsis." (PMID 37509475, 2023). "Our results are comparable to laboratory results in sepsis, with significantly higher leukocytosis, neutrophilia, band forms, and lymphopenia, as well as C-reactive protein levels > 5 μg/mL." (PMID 37368746, 2023). "One of the included studies, among ER patients with suspected infection, reported an AUC value for PCT of 0.79 for diagnosis of sepsis, which was better than that of IL-6 (AUC 0.70) or CRP (AUC 0.67)." (PMID 36941681, 2023). "According to the study’s findings, the new rapid bedside tool for salivary CRP can be a potential non-invasive method in predicting culture-positive sepsis." (PMID 36900011, 2023). "DcR3 can be used as a biomarker for sepsis and can be used alone for early diagnosis or in combination with markers such as C-reactive protein (CRP), PCT, butyrylcholinesterase, presepsin, and pro-adrenomedullin." (PMID 37629097, 2023). "Four newborns with clinical sepsis who showed increased CRP levels above 10 mg/L (20.4 mg/L; 47.5 mg/L; 52.9 mg/L; 60.7 mg/L) and seven newborns with mild neonatal infection having CRP levels above 10 mg/L at admission were excluded." (PMID 38255366, 2023). "A novel, rapid, non-invasive point-of-care device which requires less technical expertise to test CRP would be an ideal alternative to serum CRP in diagnosing sepsis." (PMID 36900011, 2023). "First, we perform laboratory tests for all newborns born to mothers with inadequate IAP; second, we treat only newborns born to febrile mothers with clinical signs of sepsis or altered biomarkers such as CRP > 15 mg/L." (PMID 37627726, 2023). "The AUC on ROC curve analysis for predicting culture-positive sepsis was 0.72 (95% CI: 0.58 to 0.86, p-value: 0.002) for serum CRP and 0.83 (95% CI: 0.70 to 0.97, p-value: <0.0001) for salivary CRP." (PMID 36900011, 2023). "Meanwhile, mediation analysis found that CRP mediates 32% of the effects of Phylum Tenericutes and class Mollicutes on sepsis (under 75 years)." (PMID 37662942, 2023). "Sepsis markers such as CRP and serum procalcitonin exhibited a significant decrease after VAC application." (PMID 38058329, 2023). "According to our study, in patients initiating CRRT, CRP, and procalcitonin were more sensitive than presepsin for sepsis diagnosis." (PMID 36832265, 2023).
Sepsis (continued). "The AUCs on ROC Curve analysis for predicting culture-positive sepsis for serum and salivary CRP 0.72 (95% CI: 0.58 to 0.86, p-value: 0.002), 0.83 (95% CI: 0.70 to 0.97, p-value: <0.0001), respectively." (PMID 36900011, 2023). "The salivary CRP had AUC 95% CI < 0.5 in predicting serum CRP > 1 mg/dL, which was used as a cut-off for sepsis screening." (PMID 36900011, 2023). "CRP concentrations were in the pathological range in all groups, but significantly higher in the sepsis groups compared with the SIRS group on Day1." (PMID 38332914, 2023). "Subsequently, multivariable and two-step MR analyses revealed that the relationship between microbiota and sepsis was mediated by CRP." (PMID 37662942, 2023). "The traditionally used markers of infection and sepsis include C-reactive protein (CRP), interleukin-6 (IL-6) and procalcitonin (PCT)." (PMID 37876167, 2023). "Laboratory tests related to inflammation in sepsis, including WBC, CRP, and neutrophils, decreased in sepsis recovery over time, except for lymphocytes." (PMID 37932249, 2023). "For pediatric sepsis, the most established biomarkers include C-reactive protein, erythrocyte sedimentation rate, procalcitonin, ferritin, serum thrombomodulin, CD64, and Il-8." (PMID 36793336, 2023). "We found three potential biomarkers (MHLA-DR expression together with CRP and sepsis index) in peripheral blood able to classify ICU patients with a high risk of developing sepsis." (PMID 37509475, 2023). "This study aimed to compare the rapid bedside quantitative assessment of C-reactive protein (CRP) in saliva to serum CRP to predict blood culture-positive sepsis in neonates." (PMID 36900011, 2023). "Nevertheless, the most common biomarkers employed in sepsis diagnosis are the CRP and procalcitonin (PCT)." (PMID 37629715, 2023). "Elevated levels of CRP+ EVs have been described in sepsis but also in myocardial infarction, and several studies have highlighted the pro-inflammatory characteristics of these CRP-bearing EVs." (PMID 38069209, 2023). "NLR is critical for the early detection and effective treatment of DFU-induced sepsis and is superior to CRP." (PMID 38026334, 2023). "The study showcased the connection between gut microbiota, CRP, and sepsis, which sheds new light on the potential role of CRP as a mediator in facilitating the impact of gut microbiota on sepsis." (PMID 37662942, 2023). "In our SIRS/sepsis cohort, the plasma sCD137 positively correlated with procalcitonin (r = 0.186, p = 0.024) and IL-6 (r = 0.181, p = 0.029), and negatively with CRP (r = −0.187, p = 0.022)." (PMID 38139346, 2023). "The diagnostic accuracy for the diagnosis of sepsis of PSP, CRP, and PCT were reported to be similar." (PMID 37176638, 2023). "Some common CRP cutoffs have been reported for sepsis (50 mg/L), particularly for neonatal sepsis (10 mg/L)." (PMID 37873776, 2023). "Procalcitonin (PCT), C-reactive protein (CRP), and complete blood count, including white blood cells, are among the most commonly analyzed sepsis-specific biomarkers also used in pneumonia in a broad range of studies." (PMID 37296721, 2023). "In the initial cohort patients with higher CRP levels had significantly more frequently cardiovascular comorbidities and infections (i.e., pneumonia and sepsis) and were treated more frequently with cardiovascular medication." (PMID 37119383, 2023). "The two most often utilized indicators for sepsis and other bacterial illnesses are C-reactive protein (CRP) and procalcitonin (PCT)." (PMID 37627950, 2023). "Up to now, regarding sepsis in general, the most widely applied routine laboratory parameters are high sensitivity C-reactive protein (hs-CRP) and procalcitonin (PCT), the latter with higher specificity than hs-CRP." (PMID 37836706, 2023). "PSP has been reported to have a higher diagnostic performance in identifying sepsis than other established biomarkers such as procalcitonin (PCT), interleukin 6 (IL-6), and C-reactive protein (CRP)." (PMID 37176638, 2023).
Sepsis (continued). "To investigate this, we compared the cellular markers DNI and MPC, and the molecular biomarkers procalcitonin and C-reactive protein (CRP) in patients presenting with suspected sepsis." (PMID 38137411, 2023). "We found that the discriminative ability of serum omentin-1 to distinguish sepsis from septic shock was similar to CRP and procalcitonin." (PMID 37241065, 2023). "Our study found 14 patients had CRP >100 mg/L at diagnosis, which is a sensitive and specific cut-off for sepsis in critical care populations, and 7 of these 14 patients had sepsis." (PMID 35130740, 2023). "Very high CRP (>200 mg/L) has been found to be a marker of sepsis, while very low CRP (<10 mg/L) was characteristic of cardiovascular diseases and viral infections." (PMID 36865442, 2023). "C-reactive protein (CRP), procalcitonin, and presepsin have been suggested as representative diagnostic and prognostic factors in critically ill patients with sepsis." (PMID 36832265, 2023). "Our results showed that inflammatory markers, including WBC, CRP, PCT and NEUT-RI, were independently associated with sepsis in critically ill patients admitted to the ICU." (PMID 37238265, 2023). "In conclusion, in-hospital mortality rates among patients with sepsis differ according to the CRP trajectory, with patients with intermediate CRP levels having the lowest mortality rate." (PMID 37709919, 2023). "This research is aimed at evaluating the clinical significance of the lymphocyte-to-C-reactive protein ratio (LCR) as an early sepsis indicator in neonates with suspected sepsis." (PMID 37197571, 2023). "We found the predictability of salivary CRP for culture-positive sepsis in this study was very good with an AUC of 0.83." (PMID 36900011, 2023). "A significant reduction in organ dysfunction and CRP was observed in the ω-3 PUFA group and was associated with a reduction in mortality in patients with less severe sepsis." (PMID 37299575, 2023). "Elevated CRP is likely a response secondary to tumor necrosis and local tissue damage; this response may be attributable to bacterial translocation from the damaged oral mucosa, endothelium, and resulting septicemia that is associated with inflammation in patients with malignancies." (PMID 37009523, 2023). "While CRP is highly sensitive, it lacks specificity for the diagnosis of sepsis; conversely, PCT is more specific but lacks sensitivity." (PMID 37509475, 2023). "A small set of biomarkers have been successfully used in the analytical diagnosis of sepsis, which include CRP, interleukin-6 (IL-6), and procalcitonin (PCT)." (PMID 37376129, 2023). "Patients with early mortality showed a significant positive correlation with elevated CRP (CRP >= 8 mg/L), higher IL-6, a medical history of sepsis, and intestinal infection." (PMID 37155023, 2023). "Together with the WBCs and the differential count, CRP has been for years the most used biomarker to identify neonates with sepsis and still remains one of the most common tests in this regard." (PMID 37627653, 2023). "The independent associations between baseline procalcitonin and the risk of 50-day in-hospital mortality were maintained after adjusting for C-reactive protein and sepsis status at admission." (PMID 36647149, 2023). "One day after sepsis induction, all animals presented peritonitis with bacterial infection as well as elevated C-reactive protein, haptoglobin, IL-1Ra, IL-6, and IL-1b." (PMID 38087374, 2023). "CRP, procalcitonin, and presepsin levels were higher in the sepsis group than in the non-sepsis group." (PMID 36832265, 2023). "The result showed no statistical difference was observed between the two groups in age, gender, underlying diseases, origins of sepsis, needing mechanical ventilation, WBC count, CRP, and ALB levels (p > 0.05)." (PMID 38298508, 2023). "Patients with liver cirrhosis had a lower CRP in comparison to the whole cohort of SIRS/sepsis patients, whereas all other parameters were similar." (PMID 38139346, 2023).
Sepsis (continued). "Regarding CRP levels, we observed higher values in patients who developed sepsis on day +3 of follow-up." (PMID 37509475, 2023). "In agreement with the presence of infection, C-reactive protein (CRP) and proportions of neutrophils were elevated and lymphocytes were reduced in the sepsis on-inclusion subgroup." (PMID 38187375, 2023). "Among patients initiating CRRT, CRP, procalcitonin, and presepsin have diagnostic value to discriminate sepsis, and procalcitonin and CRP have higher accuracy to diagnose sepsis." (PMID 36832265, 2023). "Another way to improve sensitivity would be to perform repeated or serial assessments, as shown for example for C-reactive protein, where repeated assessment within the first 24–48 hours of hospitalization in infants with sepsis improved sensitivity." (PMID 37200285, 2023). "In a recently published study, our research group used the consensus k-means clustering analysis of 25 available bedside variables including C-reactive protein and Ferritin levels at 24 h to identify 4 phenotypes in severe sepsis patients with organ failure." (PMID 36793336, 2023). "We observed significant changes in numerous CBC parameters and extended inflammation parameters (EIPs), in addition to significant biochemical analysis markers CRP and IL-6 in sepsis cohorts." (PMID 37510189, 2023). "Some studies in our included literature focused on the ability of miRNA, PCT, CRP, and other markers to jointly diagnose sepsis." (PMID 36812225, 2023). "This study aimed to apply LGMM to investigate the effects of CRP trajectories in critically ill patients with sepsis on the in-hospital mortality rate." (PMID 37709919, 2023). "In our study, sepsis was present in 73.9% of patients with a median CRP of 17.81 mg/L (range 0 to 118 mg/dl) at diagnosis." (PMID 37271816, 2023). "In this study, we compared the laboratory results between the immunocompromised group and control group on the diagnosis day of sepsis using complete blood count, hepatorenal function, coagulation function, CRP, and PCT tests." (PMID 37168393, 2023). "Small differences were seen for the PLMN sepsis group at the Day5 [CRP (p = 0.0926)] and Discharge timepoints [basophils (p = 0.1516)] only." (PMID 38332914, 2023). "The univariate analysis revealed that the patients deceased within 30 days tend to had hematological disease, glucocorticoid therapy, MOF and sepsis or septic shock, lower platelet, higher C-reactive protein and procalcitonin, agranulocytosis and higher PBS." (PMID 37260693, 2023). "In several clinical studies, PCT was found to be more accurate than CRP in differentiating sepsis and SIRS." (PMID 37147598, 2023). "Such an electrochemical sensor was intended to be used for the detection of neonatal sepsis biomarker CRP." (PMID 37366985, 2023). "First, immune-monitoring the sepsis index, CRP, and MHLA-DR expression rate biomarkers at admission and on day +3 allows an early predictive stratification of susceptible sepsis patients." (PMID 37509475, 2023). "In this study, we demonstrated that AN69ST membrane adsorbed CVVH in critically ill patients with severe sepsis and significantly decreased inflammatory parameters, including CRP, PCT, WBC, as well as secretion of inflammatory factors including IL-6 and TNF-α." (PMID 37724124, 2023). "During the first 48 h of this sepsis episode, the neonate deteriorated, requiring mechanical ventilation and possessing high inflammatory indices (max CRP value of 394 mg/L) and thrombocytopenia." (PMID 37627710, 2023). "In humans, hyperosmolar non-ketotic coma and DKA are associated with an increased risk of sepsis, systemic inflammatory response syndrome, and elevation of APP C-reactive protein." (PMID 37766698, 2023). "We conducted a comprehensive search across all databases utilizing diverse permutations of procalcitonin (PCT), C-reactive protein (CRP), sepsis, and postoperative period." (PMID 37868476, 2023).